FGL1 (fibrinogen like 1)
Diseases named in the same sentence as FGL1 in open-access papers (continued):
Sharing a sentence is not in itself a finding about the gene and the disease.
cancer (continued). "In this review, we summarize the function and molecular mechanism of FGL1 in the regulation of cancer development and metastasis and provide promising applications in therapeutic strategies for malignant tumor treatment." (PMID 34526102, 2021). "Herein, we reported for the first time that FGL1 is upregulated in both cancer tissues and plasma of ccRCC patients." (PMID 34956878, 2021). "Pearson correlation analysis showed that the expression of FGL1 in ccRCC cancer tissues was significantly negatively correlated with E-cadherin expression, whereas significantly positively correlated with N-cadherin expression." (PMID 34956878, 2021). "The results showed that FGL1 was significantly higher in cancer tissues than in the adjacent normal tissues." (PMID 34956878, 2021). "A recent work identified fibrinogen-like protein 1 (FGL1), which is a liver-secreted protein, as an additional immune inhibitory ligand that is highly expressed in human cancer cells." (PMID 34948104, 2021). "FGL-1 is upregulated in several human cancers, and genetic ablation or blockade of the FGL-1/LAG-3 interaction by monoclonal antibodies (mAbs) would enhance T-cell responses and antitumor immunity." (PMID 34917131, 2021). "Recent evidence boosted the research of FGL1 in cancer biology by illustrating a new function of FGL1 in immune suppression where it acts as a major inhibitory ligand of LAG-3 and inhibits antigen-specific T cell activation." (PMID 34956878, 2021). "The fact that FGL-1 levels in the blood of cancer patients correlates with poor prognosis and resistance to anti-PD-1/B7-H1 therapy suggests FGL-1 as a major contributor to LAG-3 immunoregulation." (PMID 33027962, 2020). "Abundantly produced by cancer cells, FGL1 plasma level is increased in cancer patients and correlates with poor prognosis." (PMID 32039024, 2019). "Elevated FGL1 was found in the plasma of cancer patients, and high FGL-1 level was correlated with poor prognosis and resistance to anti-PD-1 therapy." (PMID 31186046, 2019). "Another evaluation of 12 rat tissues and 9 human cancer cell lines showed that FGL1 was similarly liver-specific in its expression." (PMID 23483972, 2013). "FGL1 promoted lymph node metastasis, leading to cancer progression." (PMID 39085849, 2024). "The FGL1/LAG-3 interaction could potentially contribute to the resistance of anti-PD therapy in human cancers, and thus, FGL1 overexpression in the plasma of cancer patients is associated with poor prognosis and resistance to anti-PD-1/PD-L1 therapy." (PMID 38162657, 2023). "The interaction between FGL1 and LAG-3 inhibited antigen-specific T cell activation, and, more important, ablation of FGL1 in mice promoted T cell immunity, indicating that FGL1 is an attractive target in cancer immunotherapy and potentially mediates the resistance to classic ICI therapies." (PMID 37115693, 2023). "To determine whether TAMs are involved in FGL1 overexpression in liver metastatic tumors, we isolated TAMs from mouse or patient LM tissues and cocultured them indirectly with cancer cells." (PMID 37872170, 2023). "In addition, knockdown of p65 increased FGL1 ubiquitination and shortened its protein half-life in cancer cells cultured with TAM-CM." (PMID 37872170, 2023). "These traditional remedies either used holistically or on a single-component basis, could be investigated in the context of further exploring FGL1 as the therapeutic target in different cancers." (PMID 34975333, 2022). "In the future, the treatment and prognosis of various malignant tumors could be improved by adjusting the expression of FGL1 through such drugs." (PMID 35776395, 2022). "The discovery of immunotherapy via the LAG3/FGL1 axis represents a milestone in cancer treatment." (PMID 34975333, 2022). "In addition, the abnormally changed FGL1 levels in the plasma of cancer patients make it a potential predictor of cancer incidence in clinical practice." (PMID 34975333, 2022).
cancer (continued). "Elevated levels of FGL-1 in cancer may contribute to suppression of activated T cells and evasion of antitumor immunity, however, relative contributions of disrupting LAG-3 interactions with FGL-1 or MHC-II in patients is unclear." (PMID 35217575, 2022). "The downregulation of FGL1 inhibits the proliferation of cancer cells, but the upstream and downstream mechanisms that are FGL1-mediated remain unclear, warranting further exploration." (PMID 36358792, 2022). "Moreover, FGL1 expression was significantly related to individual cancer stages, as determined through the UALCAN website." (PMID 35776395, 2022). "Therefore, the FGL1 gene has been proposed as a predictor in GC patients and a target for treating this cancer type." (PMID 36011329, 2022). "Also, FGL1 was correlated with the infiltration level of CD8+T cells, monocytes, regulatory T cells (Tregs), carcinoma-associated fibroblasts (CAFs), Neutrophils and Natural killer T cell in various tumors." (PMID 35273912, 2022). "Collectively, drugs acting on the pathways of either LAG3/MHC II or LAG3/FGL1 could play a role in the cancer therapy." (PMID 33146865, 2021). "Thus, controversy remains regarding the effects of FGL1 on cancer cell progression, thereby calling for further investigation." (PMID 34069373, 2021). "First, the mechanism by which FGL1 regulates the expression of cytokines and chemokines in cancer cells remains largely unknown." (PMID 34956878, 2021). "Nevertheless, FGL1 remains a potential therapeutic target in cancer." (PMID 34956878, 2021). "FGL1 is a crucial biomarker and target for cancer immunotherapy." (PMID 33633363, 2021). "Therefore, FGL1 can be identified as a next-generation cancer immunotherapy target capable of a functional interaction with the LAG3 pathway and synergistic inhibition of T cells with PD-1." (PMID 34526102, 2021). "Novel therapeutic strategies targeting FGL1 should be further explored in the treatment of cancer." (PMID 34526102, 2021). "Finally, future studies could compare the efficacy of Nano-Gefitinib with other targeted therapies or checkpoint inhibitors (e.g., anti-FGL1/LAG-3 blockade) to determine whether combinatorial regimens yield synergistic benefits in cancer therapy." (PMID 41304988, 2025). "FGL1 blockade may have dual effects on the development of certain cancers." (PMID 38973608, 2024). "Furthermore, the authors propose that the FGL1-LAG-3 pathway could be a promising target for immunotherapy against cancer." (PMID 38390331, 2024). "Interestingly, we found FGL1 is expressed only by mesenchymal cancer cells in infiltrated tumors." (PMID 38086828, 2023). "As earlier indicated, FGL1 might be a vital marker in cancer initiation and progress." (PMID 34975333, 2022). "Finally, due to the strong double regulation of FGL1 in LUAD, FGL1 may represent a relevant therapeutic target for cancer immunotherapy, especially for LUAD." (PMID 36268014, 2022). "Another study recently found that FGL1 is an important component of the FGL1-LAG-3 pathway that promotes the growth of malignant tumors, suggesting that the double blockade of FGL1 and PD-1/PD-L1 could become a therapeutic alternative for patients for whom anti-PD therapy is ineffective." (PMID 35776395, 2022). "Furthermore, FGL1 plays important roles in cancers, and is a potential target for cancer treatment." (PMID 33867830, 2021). "Moreover, the potential of FGL1 in cancer immunotherapy was recently suggested." (PMID 34069373, 2021). "However, upregulated FGL1 is detected in several human cancers." (PMID 32467592, 2020). "However, FGL1 is normally released by the liver in low levels but by cancer in high levels." (PMID 32810392, 2020). "When FGL1 combines with LAG-3 on the surface of T cells, immune system mistake cancer cells as normal, contributing to immune-escape of tumor cells." (PMID 36911712, 2023).
cancer (continued). "Our findings add scientific content to understanding the regulation of the immune checkpoint molecule FGL1 and the functional roles of OTUD1-mediated deubiquitination in cancer immunology." (PMID 37872170, 2023). "To identify the regulatory factor controlling TAM-mediated deubiquitination and stabilization of FGL1, we performed a coimmunoprecipitation (Co-IP) assay for TAM-cocultured cancer cells followed by mass spectrometry (MS)." (PMID 37872170, 2023). "The identification of FGL1 as a functional ligand to LAG-3, suppressing T cell responses, was an exciting finding in cancer immune checkpoint inhibitors therapy." (PMID 35885017, 2022). "It was recently reported that FGL1 is a major ligand of LAG-3, which is normally secreted by the liver but is upregulated in several human cancers." (PMID 33633363, 2021). "A growing body of investigations highlights that members of FREP superfamily, such as fibrinogen-like protein-1 (FGL1), and fibrinogen-like protein-2 (FGL2), play pivotal roles in cancer and in modulating immune cell functions." (PMID 33867830, 2021). "In this review, we overview the current understandings of the roles of FGL1 and FGL2 in cancer microenvironment, and review the roles of FGL1 and FGL2 as potential immunotherapeutic targets for cancer therapy." (PMID 33867830, 2021). "FGL1 is a major ligand of LAG3, which diminishes the function of T cells and immune evasion, and is upregulated in several human cancers; its expression is limited in most of the normal tissues and is associated with poor treatment outcomes." (PMID 33632231, 2021). "Fibrinogen-like protein 1 (FGL1), elevated in many cancer patients’ plasma, binds with LAG-3 leading to poor prognosis." (PMID 34968365, 2021). "The FGL1/LAG-3 pathway can be used as a potential target for immune escape mechanisms and cancer immunotherapy." (PMID 32461587, 2020). "It is worth mentioning that no expression of PD-L1 could be observed, whereas three (HLA-DR, FGL-1, and galectin-3) of the multiple ligands for LAG-33 were highly expressed in both cancer and stromal cells." (PMID 38336861, 2024). "The expression of FGL1 and FGL2 in 20 types of cancers and their normal counterparts were measured." (PMID 38903931, 2024). "FGL1, the ligand of LAG-3, expressed on the surface of cancer cells." (PMID 36911712, 2023). "Together, the FGL1/LAG3 and PD-1/PD-L1 axes might be independently targeted in treating cancers though synergism of the two yields better therapeutic outcomes." (PMID 34975333, 2022). "Furthermore, fibrinogen-like protein 1 (FGL1) is regarded a major ligand of LAG-3 that is secreted by the liver and upregulated in several types of cancers." (PMID 35669786, 2022). "Finally, the authors proposed that the FGL1-LAG-3 pathway was an important immune escape mechanism and a potential target for checkpoint inhibitor-based cancer immunotherapy." (PMID 33633363, 2021). "FGL1 and LAG-3 are closely related to the prognosis and clinicopathological features of various types of cancer, and clinical studies have shown that dual FGL1/LAG-3 and PD-1/PD-L1 blockade therapy has promising survival benefits and long-duration response rates." (PMID 33633363, 2021). "In this study, FGL1 expression increased in DF and DHF/DSS to different degrees, suggesting that DENV virus may utilize the same immune escape mechanism as cancer cells." (PMID 31921022, 2019). "Additionally, the expression of FGL1 was significantly higher in cancer tissues (n = 90) than in adjacent non-cancerous tissues (n = 90)." (PMID 39085849, 2024). "In addition, FGL1 is involved in the epithelial-mesenchymal transformation (EMT), which is activated in the malignant progression of cancer and plays an important role in cancer development." (PMID 34975333, 2022).
cancer (continued). "FGL1 was recently identified as a major functional ligand of the immune inhibitory receptor, lymphocyte-activation gene 3 (LAG3), thus making it a promising target for cancer immunotherapy except for the classical programmed cell death protein 1/programmed cell death ligand 1 (PD-1/PD-L1) axis." (PMID 34975333, 2022). "Given the inhibitory effect of LAG3 and FGL1 on the immune response, these oncogenes may predict a negative prognosis in several cancers." (PMID 35111155, 2021). "This assay is much simpler than existing methods for determining the activity status of the FGL1-LAG-3 pathway and for designing and detecting new LAG-3/FGL1-related cancer immunotherapies based on patients’ circling FGL1, which might be convenient for use in clinical trials." (PMID 33633363, 2021). "Additionally, FGL-1 is the main immune ligand of lymphocyte-activation gene 3 (LAG-3) that negatively regulates T cells’ activation and plays a vital role in hepatocyte regeneration, glucose and lipid metabolism, as well as serving as a potential target for cancer immunotherapy." (PMID 36556955, 2022).
infection (7 papers, 2016 to 2024). The state of being infected such as from the introduction of a foreign agent such as serum, vaccine, antigenic substance or organism. "Overall, these results confirm that circ-FGL1 inhibits the apoptosis signaling pathway in A. japonicus in response to pathogen infection." (PMID 39146353, 2024). "Accordingly, these results indicated that AjMyc mediates the effects of circ-FGL1 on apoptosis upon pathogen infection." (PMID 39146353, 2024). "FgLip1 and Fgl1 are previously reported extracellular lipases in F. graminearum that are highly induced during the infection stages and in the presence of lipid sources, such as olive oil and wheat germ oil." (PMID 37093014, 2023). "The expression of 41 putative secreted effectors was altered in Δ16221_3, including the FGL1 lipase, which inhibits host callose formation to promote infection." (PMID 30934025, 2019). "Whereas the disruption of Fgl1 lipase secretion results in browning of the rachis and vascular callose depositions that impede infection." (PMID 30934025, 2019). "To further investigate the mechanisms underlying the inhibition of apoptosis by circ-FGL1 during pathogen infection, we first assessed whether circ-FGL1 could be pulled down by the Argonaute 2 (AGO2) proteins." (PMID 39146353, 2024). "Furthermore, after infection with V. splendidus, the expression levels of circ-FGL1 and AjMyc in coelomocytes exhibited opposite trends, with increased AjMyc nuclear translocation." (PMID 39146353, 2024). "While it is unknown whether levels of FGL-1 increase during malaria infection, an appealing hypothesis may be that FGL-1 contributes to inhibiting LAG-3 expressing subsets of T cells during infection, including CD8+ T cells." (PMID 33519801, 2020). "Therefore, within the rachis, where TRI gene expression is at its highest, the secretion of DON and the Fgl1 effector are both required for infection to progress throughout the wheat head." (PMID 30934025, 2019).
metabolic disease (4 papers, 2022 to 2025). A congenital disorder (due to inherited enzyme abnormality) or acquired (due to failure of a metabolically important organ) disorder resulting from an abnormal metabolic process. "Studies have also reported elevated levels of FGL1 in obese individuals, suggesting its potential as a biomarker for metabolic disorders." (PMID 38816776, 2024). "Recent research has highlighted the significant role of FGL1 in metabolic disorders, particularly in the regulation of blood lipids and glucose metabolism." (PMID 38816776, 2024). "While its official symbol is FGL1 for fibrinogen‐like 1, it is also commonly referred to as hepassocin (HPS) or HFREP1 in studies that have yielded sometimes opposite conclusions depending on the strategy used to assess the potential function of FGL1 in metabolic diseases." (PMID 40832769, 2025).
neoplastic disorder (1 paper, 2023). "The CFA16 region contains genes that may influence cardiac and neoplastic disorder risk including microtubule-associated tumor suppressor 1 (MTUS1) and fibrinogen-like protein 1 (FGL1)." (PMID 37277858, 2023).
FGL1 also shares sentences with these, for which no sentence is quoted: prostate carcinoma (5 papers); brain tumors (3); acute pancreatitis (2); Clear Cell Renal Cell Carcinoma (2); Crohn disease (2); gastrointestinal tumors (2); hyperlipidemia (2); Impaired glucose tolerance (2); triple-negative breast carcinoma (2); adenomyosis (1); adrenocortical carcinoma (1); bladder cancer (1); cyst (1); dermatitis (1); diabetic cardiomyopathy (1); endothelial dysfunction (1); Fever (1); glioblastoma (1); Glucose intolerance (1); hematologic malignancies (1); hepatitis B virus infection (1); intrahepatic cholangiocarcinoma (1); iron deficiency anemia (1); lipid metabolism disorders (1); lymph node metastasis (1); metastatic colorectal cancer (1); nephrotic syndrome (1); pneumonia (1); renal cell carcinoma (1); Sepsis (1).
A further 2 diseases each share a sentence with FGL1 in 1 paper.